SPOUT1 (SPOUT domain containing methyltransferase 1)
Description:
S-adenosyl-L-methionine-dependent RNA methyltransferase. Specifically methylates the N3 position of a uridine in 28S rRNA. Required for association of the centrosomes with the poles of the bipolar mitotic spindle during metaphase, ensuring proper spindle organization. Also involved in chromosome alignment. May promote centrosome maturation probably by recruiting A-kinase anchor protein AKAP9 to centrosomes in early mitosis. Binds specifically to miRNA MIR145 hairpin, regulates MIR145 expression at a postranscriptional level.
Synonyms: CENP-32; C9orf114; HSPC109; CENP32; NEDGSB
Tractability: Small molecule: a structure with a bound ligand is known. PROTAC: ubiquitination databases record sites on it.
Target class: Enzyme; Transferase
Gene: Protein-coding gene on chromosome 9 (128,819,651 to 128,829,815, reverse strand). Ensembl gene ENSG00000198917.
Subcellular location: Cytoplasm, cytoskeleton, spindle; Chromosome, centromere, kinetochore; Cytoplasm, cytoskeleton, microtubule organizing center, centrosome
Gene Ontology:
Molecular function: methyltransferase activity; miRNA binding; protein binding; RNA binding; RNA methyltransferase activity; rRNA (uridine-N3-)-methyltransferase activity; S-adenosyl-L-methionine binding; S-adenosylmethionine-dependent methyltransferase activity
Biological process: maintenance of centrosome location; miRNA processing; post-transcriptional regulation of gene expression; rRNA base methylation
Cellular component: kinetochore; mitotic spindle; spindle pole centrosome; centrosome; spindle
Genetic constraint (gnomAD): Loss-of-function variants: 42 observed, 55.62 expected, observed/expected ratio (o/e) 0.76, 90% interval 0.59 to 0.98. The upper end of that interval is the gene's LOEUF score, 0.98, which puts it in group 4 of 6, group 1 being the genes least tolerant of losing a copy. Missense variants: 437 observed, 490.64 expected, observed/expected ratio (o/e) 0.89, 90% interval 0.82 to 0.96. Synonymous variants: 193 observed, 194.22 expected, observed/expected ratio (o/e) 0.99, 90% interval 0.88 to 1.12.
Homologues: Orthologues: chimpanzee SPOUT1 (99% identical), dog SPOUT1 (93% identical), guinea pig SPOUT1 (91% identical), pig SPOUT1 (91% identical), mouse Spout1 (90% identical), rat Spout1 (89% identical), macaque SPOUT1 (88% identical), tropical clawed frog spout1 (67% identical), zebrafish spout1 (67% identical), Drosophila melanogaster CG12128 (48% identical), Caenorhabditis elegans spot-1 (37% identical).
Diseases named in the same sentence as SPOUT1 in open-access papers:
SPOUT1 is named in the same sentence as 18 diseases in open-access papers, as found by Europe PMC text mining. Sharing a sentence is not in itself a finding about the gene and the disease. The quoted sentences say what the papers report.
Epileptic encephalopathy (2 papers, 2024 to 2025). A condition in which epileptiform abnormalities are believed to contribute to the progressive disturbance in cerebral function. "These patients with early onset epilepsy and epileptic spasms suggest the SPOUT1 spectrum of neurodevelopmental phenotypes include developmental and epileptic encephalopathy." (PMID 39962046, 2025).
complex neurodevelopmental disorder (1 paper, 2025). A disorder that involves more than one phenotype associated with the central nervous system, including but not limited to intellectual disability, autism, and seizures (epilepsy). "In conclusion, we report here that bi-allelic variants of the SPOUT1/CENP-32 gene in humans are associated with an autosomal-recessive complex neurodevelopmental disorder: SpADMiSS." (PMID 39962046, 2025).
developmental delay (1 paper, 2025). "Commonly observed clinical findings in individuals with bi-allelic SPOUT1/CENP-32 variants included neurodevelopmental phenotypes of global developmental delay (DD) -100% (28/28), intellectual disability (ID) -100% (14/14), and seizures - 71% (20/28)." (PMID 39962046, 2025).
Hypertonia (1 paper, 2024). A condition in which there is increased muscle tone so that arms or legs, for example, are stiff and difficult to move. "Hypertonia, nystagmus, and protein-energy malnutrition might be the manifestations of SPOUT1-related patients." (PMID 40217412, 2024).
Neurodevelopmental delay (1 paper, 2025). "Aided by gene matching platforms, here we identify 28 individuals with neurodevelopmental delays from 21 families with bi-allelic variants in SPOUT1/CENP-32 detected by exome/genome sequencing." (PMID 39962046, 2025).
cancer (1 paper, 2025). A tumor composed of atypical neoplastic, often pleomorphic cells that invade other tissues. "Further studies will be required to determine whether individuals with SPOUT1/CENP-32-associated neurodevelopmental disorder have an increased risk of developing aneuploidy in vivo or even cancers." (PMID 39962046, 2025).
neurodevelopmental disorder (1 paper, 2025). A behavioral and cognitive disorder with onset during the developmental period that involves impaired or aberrant development of intellectual, motor, or social functions. "Here, the authors describe a neurodevelopmental disorder caused by bi-allelic pathogenic SPOUT1 variants with reduced activity and compromised function in spindle organization." (PMID 39962046, 2025). "We report the association of bi-allelic SPOUT1/CENP-32 variants with a complex neurodevelopmental disorder in 21 unrelated families involving 28 affected individuals." (PMID 39962046, 2025). "Collectively, the spectrum of disorders caused by disruption of centrosome/spindle related proteins have been referred to as “centrosome-based diseases”21 and the neurodevelopmental disorder associated with SPOUT1/CENP-32 variants described in this study, adds to this group of disorders." (PMID 39962046, 2025).
SPOUT1 also shares sentences with these, for which no sentence is quoted: ciliopathy (2 papers); tumour (2); early onset epilepsy (1); epilepsy (1); Epileptic spasm (1); Intellectual disability (1); liver disease (1); malakoplakia (1); microcephaly (1); Nystagmus (1); protein-energy malnutrition (1).